ALB (albumin)
Diseases named in the same sentence as ALB in open-access papers (continued):
Sharing a sentence is not in itself a finding about the gene and the disease.
Cirrhosis (continued). "Furthermore, patients with compensated cirrhosis had a significantly increased TBIL level, but a decreased ALB level." (PMID 30508917, 2018). "Odds ratios for the association between admission serum albumin levels and hospital acquired acute kidney injury (HAKI) occurrence in subgroups of patients with and without cirrhosis." (PMID 29927987, 2018). "This was further supported by the presence of liver atrophy and the characteristic alterations of cirrhosis in blood analyses, including parameters related to liver damage (transaminases, AP), liver function (bilirubin, INR, albumin) or portal hypertension and hypersplenism (thrombocytopenia)." (PMID 29907790, 2018). "Emerging recent evidence links this decreased “effective” (no longer native and reduced) albumin in decompensated cirrhosis to increased circulating PGE2-bioavailability." (PMID 30155448, 2018). "Nomogram for cirrhosis involved PLT, age, AFP, GGT, HA, Albumin, and gender." (PMID 29235488, 2017). "Univariate analysis identified the following risk factors of perioperative HBV reactivation (all P < 0.05): cirrhosis, low serum albumin, minor hepatectomy and absence of antiviral therapy." (PMID 28122361, 2017). "All but one patient who failed to achieve SVR12 were patients with advanced cirrhosis with high MELD score or low platelet count or low albumin level." (PMID 28125694, 2017). "The unadjusted levels of all LysoPA species were not different, while the ALB-adjusted levels were higher in the cirrhosis group with the exception of 22:5 and 22:6 LysoPA." (PMID 28143894, 2017). "Univariate ROC analysis identified covariates which affected surveillance performance of AFP: the c-statistics were lower in patients with cirrhosis, elevated AST levels, low albumin levels, prolonged prothrombin time, elevated baseline AFP levels, and exposure to NA therapy during study period." (PMID 27997559, 2016). "Even though none of the NAFLD or hepatitis patients had yet developed cirrhosis and there were no significant changes in their serum albumin levels in comparison to the healthy people, their TBS values had already shown various degrees of decline." (PMID 28101103, 2016). "Individuals without measurement of serum albumin, urine ketone, or hemoglobin A1C, or harboring active infection, myocardial infarction, cerebrovascular event, cirrhosis, malignancy, or overt proteinuria were excluded." (PMID 27504458, 2016). "Compared with noncirrhotic patients, the patients with cirrhosis tended to be older and more likely to have severe liver disease, lower levels of albumin, platelets, and hemoglobin, and higher blood urea nitrogen and creatinine." (PMID 27123003, 2016). "Patients lacking primary care, at diagnosis, had worse rates cirrhosis and ascites, and worse laboratory markers of liver dysfunction (e.g., lower albumin, lower platelets, higher bilirubin)." (PMID 26215250, 2015). "Patients with baseline cirrhosis were more likely to have lower levels of serum albumin (p < 0.001) and lower platelet counts (p < 0.001) than patients who had no cirrhosis at baseline." (PMID 25788199, 2015). "Unless the patient has cirrhosis, the replacement of albumin to prevent postparacentesis circulatory dysfunction is not recommended." (PMID 27335837, 2014). "The elder ages, lower levels of platelets, hemoglobin, sodium or albumin, higher levels of white blood cells, TBIL, INR or creatinine, and the presence of cirrhosis, encephalopathy (≥grade 2), HRS, or SBP revealed individual associations with short-term mortality due to ACLF (P < 0.05)." (PMID 25526495, 2014). "Clinical variables entered after PSM were age, gender, tumor size, hepatitis B virus (HBV) infection status, Child-Pugh class, cirrhosis, total bilirubin, serum AFP level, alanine aminotransferase (ALT), aspartate aminotransferase (AST), prothrombin time, albumin and platelet count." (PMID 25541684, 2014).
Cirrhosis (continued). "After multivariate analysis, only the operative time remained the only significant factor (p = 0.002), whereas ICG, LSM, albumin, platelet count, MELD score, presence of cirrhosis, HCC size and intra-operative blood loss were not significant factors." (PMID 24015232, 2013). "Albumin resuscitation was associated with higher Child-Pugh and MELD scores (P = 0.04 and P = 0.03 respectively, data not shown), suggesting that albumin was preferentially indicated to patients with advanced stages of cirrhosis." (PMID 23601847, 2013). "For example, illnesses that increase albumin loss, such as nephrotic syndrome, or diseases that decrease albumin synthesis, such as cirrhosis, will result in lower albumin levels regardless of nutritional status." (PMID 22532840, 2012). "In Group 4, patients were conservatively managed with antibiotics, non-selective beta-blocker, diu-retics, albumin infusion, proton pump inhibitor, lactulose, vitamin K injection, and specific treatment directed towards aetiology of cirrhosis." (PMID 19248644, 2009). "It is now well recognized that furosemide pharmacokinetics are not altered by cirrhosis with normal serum albumin levels." (PMID 17134488, 2006). "Serum albumin [S: 80.2 (16.8), LPS: 70.9 (15.1), Ci: 53.7 (12.8), Ci+LPS: 49.6 (8.6) mg/ml] decreased by cirrhosis (2-way ANOVA, P < 0.001) and not by LPS." (PMID 16968543, 2006). "Multivariable analysis revealed that serum albumin (sub-distribution hazard ratio [SHR], 0.51; 95% confidence interval [CI], 0.27–0.98; p = 0.042) and ammonia (SHR, 1.01; 95% CI, 1.00–1.02; p = 0.006) levels were independent factors for OHE development in geriatric cirrhosis." (PMID 40928524, 2025). "Thirdly, patients with cirrhosis or other chronic disease, were not explicitly excluded, which may have affected serum albumin levels and, consequently, PNI values." (PMID 40087583, 2025). "Still, there is a lack of data on albumin use in cirrhosis patients with septic shock." (PMID 40386509, 2025). "However, albumin and bilirubin levels remained within normal limits, indicating early to intermediate disease stages rather than advanced fibrosis or cirrhosis." (PMID 41295273, 2025). "In this review, we undertook a literature search for articles published from January 2010 on MEDLINE and Web of Science using search terms “cirrhosis”, “ascites”, “non-selective beta-blockers”, “antiplatelets”, “anticoagulants”, “albumin”, and “sodium-glucose cotransporter 2 inhibitors”." (PMID 40143117, 2025). "However, short‐term (2 weeks) administration of albumin in a multi‐centre RCT in patients hospitalised in the context of decompensated cirrhosis did not improve the development of infection, kidney dysfunction or death." (PMID 36800487, 2025). "Contrarily, in the randomized ATTIRE study, the prophylactic use of albumin in patients with decompensated cirrhosis could not prevent infections, AKI and death in the short term, thus increasing the number of patients with congestion." (PMID 38726210, 2024). "Notably, there are no effective results indicating that short-term albumin infusion can reduce mortality in patients with decompensated cirrhosis that present with different complications." (PMID 38551716, 2024). "The age–male–albumin–bilirubin–platelets (aMAP) risk scoring system was recently created to assess HCC risk in chronic hepatitis patients, including HCV carriers with SVR, again both in the presence or absence of cirrhosis." (PMID 39772206, 2024). "High albumin gradient (SAAG greater than or equal to 1.1 g/dL) is obtainable in the following conditions: heart failure, constrictive pericarditis, alcoholic hepatitis, cirrhosis, Budd-Chiari syndrome, portal vein thrombosis, idiopathic portal fibrosis, and massive hepatic metastasis." (PMID 38899262, 2024).
Cirrhosis (continued). "Albumin was more likely to be administered to patients with more severe illness and greater medical complexity, as indicated by higher Model for End-Stage Liver Disease-Sodium (MELD-Na) scores, advanced stages of AKI, and increased rates of cirrhosis complications." (PMID 39434907, 2024). "These biochemical markers reflect liver synthetic function (albumin), damage and inflammation (AST, ALT and GGT), cholestasis (total bilirubin, ALP and GGT), and portal hypertension (platelet count), and thus may facilitate the diagnosis of cirrhosis." (PMID 39666107, 2024). "Currently, no research has explored whether albumin therapy can improve outcomes in ICU patients with cirrhosis and non-HRS AKI." (PMID 39434907, 2024). "First, the GLOBE and UK-PBC scores incorporate multiple key independent variables such as age, bilirubin, ALP, albumin, and platelet count, unlike other criteria that solely focus on treatment response and may not account for cirrhosis." (PMID 39124763, 2024). "In addition, many patients with cirrhosis do not show a decrease in platelets or albumin and are often diagnosed in the advanced stages of cirrhosis, hepatocellular carcinoma, or ruptured esophageal varices." (PMID 38004284, 2023). "Albumin levels and serum zinc concentrations were correlated regardless of the presence or absence of cirrhosis, but the strength of the correlation differed between the presence and absence of cirrhosis." (PMID 36701704, 2023). "However, several studies have suggested that BCAA supplementation in patients with compensated cirrhosis and albumin levels greater than 3.6 g/dL or with a BTR of 4 or less may prevent a future drop in albumin." (PMID 36765884, 2023). "However, when comparing HCC with underlying liver cirrhosis versus cirrhosis without HCC, sAxl, Gas6 or their albumin ratios exhibited no discriminatory power." (PMID 37532736, 2023). "Patients with cirrhosis are more susceptible to prerenal AKI due to the use of diuretics, gastrointestinal fluid loses caused by laxatives in prevention of liver encephalopathy, and large volume paracentesis without albumin supplementation." (PMID 38139297, 2023). "No variation was observed in the prevalence of cirrhosis (p = 0.475); consistently, no significant changes were observed in liver function parameters (platelet count, p = 0.180; albumin, p = 0.446; total bilirubin, p = 0.382) and in Child–Pugh score (p = 0.968)." (PMID 35323319, 2022). "However, age, gender, tumor diameter, etiology of liver disease, cirrhosis, ascites, ALT, AST, TBIL, neutrophil count, lymphocyte count, albumin, differentiation degree, arterial rim enhancement, tumor capsule, and enhancement pattern were not statistically significant (P > 0.05)." (PMID 35444942, 2022). "In this study, we hypothesized that serum albumin and ammonia levels, both of which are involved in the pathogenesis of HE, could be useful in establishing a simple screening model for CHE based on blood biochemical parameters in patients with cirrhosis." (PMID 36449492, 2022). "We demonstrate that albumin infusions to increase serum albumin >30 g/L in hospitalized patients with decompensated cirrhosis had no immunomodulatory or anti-inflammatory effect, nor improved circulating albumin function over standard care, in which little albumin was administered." (PMID 35333783, 2022). "Among patients treated with preferred DAAs, cirrhosis, HBV coinfection, BMI ≥25, HbA1c ≥ 6.5, HOMA index ≥2, triglyceride ≥150 mg/dl, the use of sofosbuvir-based or EBR/GZR regimens, pre-therapy ALT ≥1xULN, higher AST, AFP, T-Bil, and lower albumin level was found." (PMID 34566631, 2021). "However, the role of albumin in the management of GIB in patients with decompensated cirrhosis has not yet been assessed." (PMID 32576140, 2020). "Furthermore, multivariate analysis identified a serum ALB level <3.95 before DAA treatment as an independent factor that contributed to the development of HCC in patients without cirrhosis." (PMID 33284844, 2020).
Cirrhosis (continued). "Similarly, the presence of cirrhosis, portal vein invasion/thrombosis, extent of hepatopulmonary shunt fraction, and baseline bilirubin and albumin levels had no prognostic value on survival." (PMID 31881761, 2019). "The most important risk factors for HCC irrespective of underlying cirrhosis etiology were older age, male sex, Hispanic ethnicity, high serum AFP level, alkaline phosphatase level and AST/√ALT ratio, and low platelet count and serum albumin level." (PMID 30260995, 2018). "The possible reason is that albumin level measured during hospitalization did not reflect the patient’s severity of disease because albumin was commonly administrated in inpatients with cirrhosis." (PMID 28061757, 2017). "In this study, the use of midodrine and octreotide significantly improved serum sodium concentration and urinary EFWC in our small group of patients with cirrhosis complicated by ascites (as evidence of portal hypertension) and whose hyponatremia failed to improve with albumin challenge for 48 h." (PMID 28352627, 2017). "Consistent with the qPCR data, Western blotting indicated no significant changes in albumin or TTR expression (both P values > 0.05) in the liver tissue of rats with cirrhosis, whereas albumin and TTR levels were increased in rats treated with DPSCs (both P values < 0.05)." (PMID 29150644, 2017). "Non-cirrhotic CHB patients had higher albumin levels than patients with cirrhosis or HCC." (PMID 27694815, 2016). "Although liver biopsy is the only way to definitely confirm cirrhosis and serum albumin is not indicated as a screening tool for cirrhosis, the evaluation of blood albumin levels can be used to help grade the severity of cirrhosis and further infer liver synthetic function." (PMID 26290513, 2016). "Finally, the values of both AOPPs-albumin and hs-TnT in CHC patients with a low Child-Pugh score and absence of ascites suggest that AOPPs might have a role in the late stages of cirrhosis by aggravating the already initiated cardiac dysfunction." (PMID 26665009, 2015). "The higher serum albumin, lower ascites and reduced edema summarized in our data accord well with the clinical situation, because the most common reason for ascites and edema in HCC patients complicated by cirrhosis was hypoproteinemia, which can be greatly improved by supplementation with BCAAs." (PMID 26155840, 2015). "In the SOFA-matched group, the patients with cirrhosis had a lower platelet count (P < .001), a higher Glasgow coma scale (GCS), a more stable haemodynamic status, more favourable renal function, a higher bilirubin level, and a lower albumin level compared with the patients without cirrhosis." (PMID 25580088, 2014). "Moreover, since the liver is the site of synthesis and degradation of carrier proteins thyroxin binding globulin (TBG), thyroxin-binding prealbumin (TBPA) and albumin, it is well-established that defective hepatocellular uptake and inefficient production of TBG are present in cirrhosis." (PMID 22919507, 2012). "Based on the relationship of the regression coefficients of four-biochemical markers, ALP, bilirubin, albumin and platelet count, we developed a new fibrosis-cirrhosis index for the prediction of HCV disease progression from initial fibrosis stage to end stage cirrhosis." (PMID 21507271, 2011). "This study concluded that a simple index (FCI) containing ALP, bilirubin, albumin and platelet count may accurately classify different fibrosis stages from none to cirrhosis." (PMID 21507271, 2011). "However, all differences in amino acid concentrations retained their significance in when only patients without cirrhosis and with normal bilirubin and albumin were compared to healthy controls." (PMID 15790420, 2005).
Cirrhosis (continued). "Perhaps continuation of targeted albumin infusions beyond 2 weeks, which had been shown to have beneficial effects in the ANSWER trial, could be further investigated in patients with decompensated cirrhosis, especially those with higher organ system disconnection (see graphical abstract)." (PMID 37019645, 2023). "Only 20 hospitalized adult patients with cirrhosis and ascites, without other identifiable causes of AKI, met all criteria for a clinical diagnosis of HRS-AKI after receiving standardized volume administration with albumin and withdrawal of diuretics, followed by an IVC US evaluation." (PMID 36866858, 2023). "However, the effect of albumin infusion in cirrhosis with GIB has not been systemically studied." (PMID 32576140, 2020). "Notably, although the between-group differences (CLD/no CLD and cirrhosis/no cirrhosis) in many laboratory parameters, mainly hemoglobin, albumin, and cholesterol, were statistically significant, the actual differences were relatively small, apparently because of the difference in group size." (PMID 30973940, 2019). "Additionally, albumin infusion may also decrease the in-hospital mortality of patients with cirrhosis regardless of overt HE." (PMID 31596729, 2019). "AST, ALT, albumin, platelet count, prothrombin time, hyaluronic acid, AFP, and PIVKA-II that were associated with cirrhosis by univariate analyses were excluded because they were apparently the result of cirrhosis but not the causes for the progression to cirrhosis." (PMID 25713769, 2015). "The cut-off values of serum albumin levels for predicting CHE were 3.2 g/dL in one study of 311 patients with cirrhosis and 3.15 g/dL in another study of 27 patients with cirrhosis aged under 65 years and without portosystemic shunt." (PMID 40142666, 2025). "Platelet, INR, albumin, total bilirubin, and white blood cell levels, which reflect liver functions, differed significantly between HCC subjects with and without cirrhosis (P < .05)." (PMID 39128067, 2024). "SB increased the serum albumin levels that were reduced in cirrhosis in one RCT, but not in a rat cirrhosis model." (PMID 39203520, 2024). "In our study focusing on ICU patients with cirrhosis and AKI, albumin therapy did not affect the 28-day mortality rate in the overall population." (PMID 39434907, 2024). "In non-cirrhosis patients, none of the SM species correlated with the MELD score, ALT, AST, bilirubin, albumin, INR, CRP, leukocytes, platelets, or creatinine." (PMID 37176109, 2023). "A unordered multicategorical logistic regression analyses showed that the age, TBIL, ALT, ALB, PT, GGT and GPR help identify non-hepatic disease, hepatitis, cirrhosis, and hepatocellular carcinoma." (PMID 36890811, 2023). "Although such data points would serve as interesting additions to future research in the context of cirrhosis and AKI, we posit that they are unlikely to alter the main finding of our study that timely albumin administration improves patient outcomes." (PMID 39132612, 2023). "HRS-AKI can only be diagnosed in a patient with decompensated cirrhosis and AKI without improvement in kidney function after diuretic withdrawal and plasma volume expansion with albumin infusion (1 g/kg body weight per day) for 2 days." (PMID 37510105, 2023). "Using Cox regression models, we have also shown that serum LN and CIV levels predict occurrence of decompensation event independent of age, etiology of cirrhosis, esophageal varices, ALP, GGT, ALB level, PLT counts, MELD score, and FIB-4 index." (PMID 37726681, 2023). "This suggests that the age, TBIL, ALT, ALB, PT, GGT, and GPR are useful for identifying patients with AFP-negative non-liver disease, hepatitis, cirrhosis, and HCC but are of limited value." (PMID 36890811, 2023). "In this regard, a recent report of a multicenter phase 1/2a trial for patients with cirrhosis found that low doses of PRI-724 significantly improved liver stiffness and reduced serum albumin levels, but not fibrosis." (PMID 36551548, 2022).